FAM86B2 (family with sequence similarity 86 member B2)
Tractability: PROTAC: ubiquitination databases record sites on it.
Gene: Protein-coding gene on chromosome 8 (12,424,408 to 12,436,408, reverse strand). Ensembl gene ENSG00000145002.
Subcellular location (Human Protein Atlas): Vesicles
Gene Ontology:
Molecular function: protein binding; protein-lysine N-methyltransferase activity
Cellular component: protein-containing complex
Genetic constraint (gnomAD): Loss-of-function variants: 1 observed, 7.46 expected, observed/expected ratio (o/e) 0.13, 90% interval 0.047 to 0.64. That is too few expected variants to judge how well the gene tolerates losing a copy. Missense variants: 20 observed, 63.14 expected, observed/expected ratio (o/e) 0.32, 90% interval 0.22 to 0.46. Synonymous variants: 5 observed, 22.76 expected, observed/expected ratio (o/e) 0.22, 90% interval 0.11 to 0.46.
Homologues: Orthologues: dog EEF2KMT (77% identical), mouse Eef2kmt (70% identical), rat Eef2kmt (70% identical), tropical clawed frog eef2kmt (50% identical), zebrafish eef2kmt (43% identical), Drosophila melanogaster CG7889 (27% identical), Caenorhabditis elegans R08D7.4 (25% identical). Paralogues in human: EEF2KMT (92% identical), FAM86B1 (89% identical).